DARS2 (aspartyl-tRNA synthetase 2, mitochondrial)
Diseases named in the same sentence as DARS2 in open-access papers (continued):
Sharing a sentence is not in itself a finding about the gene and the disease.
respiratory infections (1 paper, 2024). "The studies also raise the opportunity for testing utility of DARS2 recombinant peptides in immunodeficient patients with respiratory infections." (PMID 39039092, 2024).
serous ovarian cancer (1 paper, 2023). "DARS2 has recently aroused the interest of researchers and has been found to be up-regulated in HCC, BLCA and high-grade serous ovarian cancer." (PMID 37626419, 2023).
tumor (15 papers, 2017 to 2025). "Further, the loss-of-function assays demonstrated that silencing of DARS2 significantly inhibited the LUAD tumor growth by inactivating the PI3K/AKT signaling pathway." (PMID 38361754, 2024). "Conversely, lower expression of DARS2 results in increased susceptibility of tumor cells to Jurkat cell-mediated cytotoxicity." (PMID 38299141, 2023). "Furthermore, NFAT5 acts as a tumor suppressor in HBV-associated HCC tissues by suppressing DARS2 expression." (PMID 29052520, 2017). "Furthermore, NFAT5 acts as a tumor suppressor in HBV-associated HCC tissues by suppressing DARS2 expression, indicating that DARS2 may be a potential target for the treatment and diagnosis of HCC." (PMID 36017335, 2022). "DARS2 knockdown significantly reduced tumor size and weight, an effect partially reversed by PINK1 overexpression." (PMID 39990673, 2025). "Both in vitro and in vivo experiments confirmed that DARS2 inhibited cellular senescence and facilitated tumor progression by enhancing PINK1-mediated mitophagy." (PMID 39990673, 2025). "Collectively, these results show that DARS2 is a key regulator of BCa progression, potentially via its involvement in mitophagy and tumor cell survival." (PMID 39990673, 2025). "It has been further confirmed that inhibition of DARS2 expression can significantly suppress the proliferation of ESCA tumor cells." (PMID 38382106, 2024). "In this study, we specifically focus on the relationship between DARS2 and tumor cell proliferation, migration, cell cycle, glycolysis, m6A, and ceRNA." (PMID 38382106, 2024). "In terms of T staging, DARS2 expression was higher in tumor samples of T1, T2, and T3 stages compared to the normal group (p < 0.05)." (PMID 38382106, 2024). "Regarding N staging, DARS2 expression was higher in tumor samples of N0, N1, and N3 stages compared to the normal group (p < 0.05)." (PMID 38382106, 2024). "At the same time, it can also be seen that the silenced DARS2 increased the apoptosis rate, indicating that knocking down DARS2 can significantly promote tumor cell apoptosis." (PMID 38382106, 2024). "The research findings revealed that DARS2 expression was elevated in tumor samples of all stages (I, II, III, and IV) compared to the normal group (p < 0.05)." (PMID 38382106, 2024). "In terms of M staging, DARS2 expression was higher in tumor samples of M0 and M1 stages compared to the normal group (p < 0.05)." (PMID 38382106, 2024). "Lastly, we conducted in vivo experiments to validate the impact of DARS2 knockdown on tumor formation." (PMID 38299141, 2023). "This indicates that in the immune microenvironment, elevated expression of DARS2 can lead to a reduction in the cytotoxicity of Jurkat cells against tumor cells." (PMID 38299141, 2023). "In summary, the results of this study indicate that DARS2 is highly expressed in LUAD tissue and is associated with tumor differentiation, N-stage, and TNM stage." (PMID 37626419, 2023). "Conversely, overexpression of DARS2 resulted in heightened activity of tumor cells in the co-culture." (PMID 38299141, 2023). "In this study, we found through GSEA that changes in DARS2 in the LUAD patient dataset resulted in a significant enrichment of glycolysis pathways in tumor cells." (PMID 37626419, 2023). "IHC images of tumor tissues showed a decrease in both DARS2, cell proliferation markers Ki67 and the immune marker PD -L1 after DARS2 knockdown." (PMID 38299141, 2023). "In the co-culture setting, we observed lower activity in tumor cells of the DARS2 knockdown group compared to the control group." (PMID 38299141, 2023). "This study further demonstrates the important role of DARS2 in tumor metabolic pathways and its close relationship with glycolysis of tumor cells and 18F-FDG PET/CT imaging." (PMID 37626419, 2023).
tumor (continued). "Interfering with the expression of DARS2 can significantly inhibit the proliferation and migration of tumor cells, and further inhibit the glycolytic ability of LUAD cells by affecting the expression of key glycolytic genes." (PMID 37626419, 2023). "Wilcoxon rank sum test results showed that in TCGA LUAD, GSE19188 and GSE30219 datasets, there was a significant increase in DARS2 expression in the tumor group compared to the normal group (p < 0.001)." (PMID 37626419, 2023). "Although the role of DARS2 in tumor research needs further in-depth exploration and research, its important role in tumor metabolic pathways has received increasing attention." (PMID 37626419, 2023). "Protein immunoblotting results further demonstrated elevated expression of DARS2 in both cancer cell lines and tumor tissues." (PMID 38299141, 2023). "To gain a more comprehensive understanding of its role in tumor immune regulation, we conducted co-culture experiments with DARS2 and Jurkat cells, with further validation through animal experiments." (PMID 38299141, 2023). "Future research can explore the potential application value of DARS2 in tumor therapy and molecular imaging of tumor cells." (PMID 37626419, 2023). "The results showed higher tripartite motif containing 71 [TRIM71] expression in BLCA tissues compared to that in non-tumour tissues, while DARS2 and RBMS3 expression levels were downregulated in tumour tissues." (PMID 33685397, 2021). "Subsequent experiments showed that DARS2 expression was higher in HCC tissues than in para-tumor tissues and that DARS2 regulated the cell cycle progression and apoptosis of HCC cells." (PMID 29052520, 2017). "In addition, IHC analysis of the tumor tissues confirmed that DARS2 knockdown considerably reduced PINK1 and CDK4 expressions, which were partially restored upon PINK1 overexpression, consistent with our earlier findings." (PMID 39990673, 2025). "Furthermore, in the histological grade analysis, DARS2 expression was higher in tumor samples of G1, G2, and G3 stages compared to the normal group (p < 0.05)." (PMID 38382106, 2024). "Cell cycle analysis revealed that compared to the control group, tumor cells in the experimental group were arrested at the S and G2/M phases, indicating that sustained expression of DARS2 may disrupt the normal cell cycle progression in tumor cells." (PMID 38382106, 2024). "Materials and methods: Transcriptional data of pan-cancer and ESCA were downloaded from UCSC XENA, TCGA, and GEO databases to analyze the differential expression of DARS2 between tumor samples and normal samples, and its correlation with clinicopathological features of ESCA patients." (PMID 38382106, 2024). "Furthermore, lactate production experiments demonstrated significantly lower lactate production in ESCA tumor cells after DARS2 interference (p < 0.05)." (PMID 38382106, 2024). "In contrast to Wang’s findings, we speculate that the upregulation of PD-L1 induced by high DARS2 expression may weaken the cytotoxicity of CD8+ T cells against tumor cells." (PMID 38299141, 2023). "In summary, high DARS2 expression may promote tumor development by altering the immune microenvironment of BLCA." (PMID 38299141, 2023). "We analyzed TCGA data to investigate the expression of DARS2 in tumor and normal tissues." (PMID 38299141, 2023). "Additionally, we delved into the impact of DARS2 interference on tumor cell proliferation, invasion, migration, and PD-L1 expression." (PMID 38299141, 2023). "In addition, the expression level of DARS2 is closely related to the 18F-FDG PET/CT metabolic parameters of tumor cells." (PMID 37626419, 2023). "Additionally, analysis of paired mRNA expression data from TCGA showed a significant increase in DARS2 expression in tumor tissues (P<0.001)." (PMID 38299141, 2023). "Furthermore, we found that DARS2 mRNA and protein expression was higher in tumor tissues than in non-tumor tissues." (PMID 29052520, 2017).
tumor (continued). "Patients with a tumor diameter greater than 2 cm exhibited lower DARS2 expression." (PMID 29052520, 2017). "DARS2 may be involved in multiple biological pathways related to tumor development." (PMID 38382106, 2024). "Flow cytometry analysis revealed that compared to the control group, tumor cells in the experimental group were found to be arrested in the S phase and G2/M phase (p < 0.05), suggesting that inhibition of DARS2 expression may disrupt the normal cell cycle progression in tumor cells." (PMID 38382106, 2024). "Moreover, we observed that tumor cells with high DARS2 expression exhibit enhanced relative activity, while the knockdown group showed the opposite, further confirming the stronger immunosuppressive effect of tumor cells with high DARS2 expression." (PMID 38299141, 2023). "DepMap demonstrated that the deletion of UBC, DARS2, and DCXR significantly inhibited tumor cell proliferation, asserting their roles in maintaining tumor growth." (PMID 39990673, 2025). "In this study, the comprehensive application of bioinformatics analysis enabled the prediction of DARS2 expression in tumors, while the regulatory capacity of DARS2 in ESCA tumor cells was successfully validated via cellular assays." (PMID 38382106, 2024). "In our study, we have demonstrated that DARS2 downregulation inhibited LUAD cell proliferation, migration, and invasion abilities, substantially retarding tumor growth in vivo by inactivating the PI3K/AKT signaling pathway." (PMID 38361754, 2024). "At the same time, we retrospectively analyzed the correlation between DARS2 expression and PET/CT metabolic parameters in tumor sections of 62 patients with LUAD to analyze the potential relationship between DARS2 and glycolysis of LUAD." (PMID 37626419, 2023). "In vitro cell experiments have confirmed that interfering with the expression of DARS2 can significantly inhibit the proliferation and migration of LUAD cells, and can significantly promote tumor cell apoptosis." (PMID 37626419, 2023). "While three genes (AHNAK, ABCC9, and DIP2C) were highly expressed in normal tissues, eight genes (CHMP4C, CLIC3, DARS2, PLOD1, POU5F1, RAD9A, RUNX2, SLC3A2) were highly expressed in tumour tissues." (PMID 36685927, 2022). "DARS2 (mitochondrial aspartyl-tRNA synthetase) was strongly upregulated in HCC, and the increase in DARS2 expression was correlated with tumor size, cell differentiation, distal metastasis, and portal vein invasion in HCC and a shorter survival time." (PMID 36017335, 2022). "Through the HPA database, we found that three genes (ABCC9, AHNAK, and DIP2C) had low expression in patients with tumours, whereas eight genes (PLOD1, SLC3A2, RUNX2, RAD9A, CHMP4C, DARS2, CLIC3, and POU5F1) were highly expressed." (PMID 36685927, 2022). "Upregulated genes were primarily associated with cell adhesion/invasion/metastasis (ELMO2, ADAM9, DLG1, TRPM7), metabolism/mitochondrial function (FAM120A, DARS2), and cellular transport/axonal trafficking (KIF1B, TBC1D5), indicating the presence of tumor microenvironment stress." (PMID 41404060, 2025). "Knockdown DARS2 and COX5B inhibited tumor cell proliferation." (PMID 41502520, 2025). "Although it has been concluded that the expression level of DARS2 may affect cell proliferation, migration, and apoptosis, we still need to further elucidate its mechanism, as more and more people believe that most cancer deaths are caused by metastasis rather than local tumor growth." (PMID 38382106, 2024). "Our data showed that DARS2 silence not only regulated the LUAD cell proliferation, migration, and invasion abilities and triggered apoptosis in vitro but also achieved substantial tumor inhibition in vivo." (PMID 38361754, 2024).
tumor (continued). "In vitro cell experiments have shown that interfering with DARS2 expression can inhibit the proliferation and migration of LUAD cells, promote cell apoptosis, and inhibit the glycolytic activity of tumor cells by inhibiting the expression of glycolytic related genes SLC2A1, GPI, ALDOA, and PGAM1." (PMID 37626419, 2023). "Eight genes (SLC3A2, DARS2, DIP2C, PLOD1, RUNX2, ABCC9, AHNAK, and CLIC3) may be involved in the malignant transformation of tumours, and three genes (CHMP4C, POU5F1, and RAD9A) may have a protective effect in patients with tumours." (PMID 36685927, 2022). "Through the HPA database, we found that three genes, namely ABCC9, AHNAK, and DIP2C, had low expression in patients with tumours, and eight other genes—PLOD1, SLC3A2, RUNX2, RAD9A, CHMP4C, DARS2, CLIC3, and POU5F1—were highly expressed in patients with tumours." (PMID 36685927, 2022). "The result showed that the more DARS2 protein were stained in tumor tissues than in non-tumor tissues in immunohistochemistry assays, suggesting that DARS2 is upregulated in HCC tissues." (PMID 29052520, 2017). "Although DARS2 has not been identified in previous tumor studies, its biological function is well documented." (PMID 29052520, 2017). "Interestingly, DARS2, which has never been related to BC, is upregulated in our analysis (10 out 12 tumor samples are classified as high) and has been associated with hepatocarcinogenesis, demonstrating its putative implication in BC." (PMID 35453681, 2022). "However, DARS2 has not been previously studied in any tumor disease." (PMID 29052520, 2017). "Moreover, some other non-structural nuclear MTRGs, such as SUCLA2, DARS2, and TRMU, can regulate tumor cells and influence the prognosis of cancer patients." (PMID 34692528, 2021).
cancer (11 papers, 2020 to 2025). A tumor composed of atypical neoplastic, often pleomorphic cells that invade other tissues. "Although the overexpression and carcinogenic function of DARS2 in other cancers have been confirmed, the precise involvement and underlying biological mechanism of DARS2 in ESCA remains inadequately comprehended." (PMID 38382106, 2024). "DARS2 exhibited dependency in 315 of 1,150 cell lines, implying its importance across several cancer contexts." (PMID 39990673, 2025). "Of these genes, DARS2 was identified as a key regulator that significantly affected cancer progression." (PMID 39990673, 2025). "The aberrant intracellular expression of a mitochondrial aspartyl-tRNA synthetase 2 (DARS2) has been reported in human cancers." (PMID 38361754, 2024). "Proliferating cells prefer aerobic glycolysis, and DARS2 is preferentially expressed in proliferating cells, including cancer cells." (PMID 38382106, 2024). "Motivated by these facts and considerations, this study demonstrated the role of DARS2 expression in The Cancer Genome Atlas (TCGA)-LUAD cohort through the Gene Expression Profiling Interactive Analysis (GEPIA) database." (PMID 38361754, 2024). "In order to determine the expression profile of DARS2 in the majority of common cancers, we performed a pan-cancer analysis based on the TCGA and GTEx databases." (PMID 38382106, 2024). "Cell and animal experiments validated that DARS2 knockdown and overexpress can inhibit or increase cancer cell proliferation, metastasis, tumorigenesis, immune escape, and PD-L1 levels." (PMID 38299141, 2023). "The results showed an increase in DARS2 mRNA expression in four pairs of cancer tissues compared to adjacent normal tissues." (PMID 38299141, 2023). "Treatment strategies aimed at DARS2 regulating mitochondrial function and glycolytic pathways can bring new possibilities for cancer treatment and provide more effective methods and means for clinical personalized treatment and imaging." (PMID 37626419, 2023). "Previous reports highlighted the critical role of DARS2 in cancer progression." (PMID 38361754, 2024). "While the impact of DARS2 has been explored in other types of cancer, its exact function in ESCA remains unclear." (PMID 38382106, 2024). "TARS1, VARS1, CARS2, DARS2, and YARS2 are associated with unfavorable outcomes in two cancer types." (PMID 33266490, 2020). "Specific aaRSs that are differentially upregulated across many cancer types include TARS1 (n = 23), DARS2 (n = 22), GARS1 (n = 21), YARS2 (n = 21), EPRS1 (n = 20), AIMP2 (n = 19), and FARSA (n = 18)." (PMID 33266490, 2020). "The results revealed elevated expression of both DARS2 and PD-L1 in cancer tissues compared to adjacent non-cancerous tissues across all five sample sets." (PMID 38299141, 2023).
mitochondrial disease (5 papers, 2013 to 2024). "DARS2 is a mitochondrial tRNA synthetase with defects associated with many neurological and mitochondrial diseases." (PMID 37626419, 2023). "Many patients with mitochondrial diseases consistently have normal lactic acid levels, even it has been described pathogenic mutations in DARS2 where elevated lactate was only observed in the affected tissue (white matter) and not in blood or cerebrospinal fluid." (PMID 24034276, 2013).
infection (4 papers, 2014 to 2025). The state of being infected such as from the introduction of a foreign agent such as serum, vaccine, antigenic substance or organism. "As with other tRNA‐synthetases, DARS2 is secreted from multiple cell types during infection to potentiate the immune response." (PMID 41214844, 2025). "While DARS2 has been demonstrated to be released during infection and acts to stimulate cytokine secretion and immune cell chemotaxis, its role in response to cytokine signaling remains unknown." (PMID 41214844, 2025). "Hence, we observed significantly increased levels of circulating DARS2 for weeks in a cohort of patients with bacterial culture-positive infections." (PMID 39039092, 2024). "Knockdown of DARS2, but not related mt-aaRS in BEAS-2B cells significantly attenuated the release of the innate immune cytokines IL-1β, IL-6, and TNFα in response to infection with PA103." (PMID 39039092, 2024). "Interestingly, the level of cAMP and the phosphorylation of Cmk1 in DARS1 was higher than that in the DARS2; however, the pathogenicity of DARS1 was not attenuated during the infection of cucumber leaves." (PMID 25275394, 2014).
bacterial infection (1 paper, 2024). "The behavior of DARS2 as a secreted protein with immunostimulatory activity may reflect an intrinsic defense mechanism in response to systemic or localized bacterial infection." (PMID 39039092, 2024). "Interestingly, while FBXO24 was observed to be induced in transplant-rejected lung samples positive for bacterial infection, we also observed increased plasma levels of DARS2 in infected patients." (PMID 39039092, 2024). "Through DARS2 disposal in cells we uncover a previously undescribed immunoregulatory function of a ubiquitin E3 ligase subunit that can be exploited to develop non-antibiotic therapeutics for bacterial infections." (PMID 39039092, 2024).
psychiatric disorder (1 paper, 2021). A disorder characterized by behavioral and/or psychological abnormalities, often accompanied by physical symptoms. "DARS2 is suggested to act as a potential molecular marker of early life stress and vulnerability to psychiatric disorders, and CSE1L plays a role in cellular proliferation and apoptosis." (PMID 34641990, 2021).